IL6 (interleukin 6)
Diseases named in the same sentence as IL6 in open-access papers (continued):
Sharing a sentence is not in itself a finding about the gene and the disease.
melanoma (continued). "To study the effect of IL-6 on melanoma-microglia interactions, we employed the 3D co-culture tumor spheroid model." (PMID 37296634, 2023). "The integration of the data presented in this study show that melanoma cells prompt microglia reprogramming via different variations of IL-6-mediated activation of STAT3." (PMID 37296634, 2023). "BRAF V600E melanoma cells have been found to produce key cytokines involved in inflammation such as IL-1β, IL-6, IL-8, and TGF-β as signals, for instance, for neutrophil recruitment." (PMID 37627054, 2023). "Studies show that high interleukin 6, interleukin 8, and PDGF-AB/BB levels in melanoma are associated with poor patient survival." (PMID 37445794, 2023). "Microglia cells exposed to melanoma-derived IL-6 exhibited upregulated levels of STAT3 phosphorylation and SOCS3 expression, which, in turn, promoted melanoma cell viability and metastatic potential." (PMID 37296634, 2023). "The opposite effects of TGF-β in melanoma is associated with the deregulation of cytokines (TNF-α, VEPH1, SMAD4, INF-γ, SKI) and signaling pathways (Notch1, IL-6, and Erk/MAPK pathway), which in return regulate TGF-β signaling." (PMID 35461253, 2022). "Melanoma involves upregulation of pro-inflammatory cytokines, such as IL-6, IL-8, C-C chemokine ligand 5 (CCL5), and IL-1β, along with VEGF." (PMID 35334544, 2022). "In met-low melanoma cells, overexpression of IL-6 was a sufficient signal to educate MDPs to induce metastasis and metastatic switch." (PMID 36429126, 2022). "There were six clusters including melanoma, IL-6, ROS, oxidative stress, sulforaphane, and thieleanin." (PMID 36124033, 2022). "Previously, we showed that combined inhibition of elevated WNT5A and IL-6 signaling reduced the invasion and migration of BRAFi-resistant (BRAFi-R) melanoma cells." (PMID 36551563, 2022). "Weber and co-workers recently observed in a murine melanoma model that IL-6 induced CCR5 expression and thus induced potent immunosuppressive activity of MDSC in the TME." (PMID 36429126, 2022). "In a study on melanoma, IL6-overexpressing tumors were found to grow significantly slower in mice with concomitant CD8+ T cell activation." (PMID 36506508, 2022). "Of note, two-dimensional culture of human melanoma cells with DCs revealed that prostaglandin E2 and IL-6 released from the melanoma cells converted cDC2s into CD14+ cDCs, which are characterized by an immunosuppressive phenotype." (PMID 35454882, 2022). "We found that a combined treatment with relatively high concentrations of the WNT5A antagonist Box5 and the IL-6 blocking antibody resulted in approximately 50% inhibition of BRAFi-R melanoma cell invasiveness." (PMID 36551563, 2022). "This identifies another critical mechanism in melanoma immune response avoidance and makes IL-6 a promising target for melanoma immunotherapy." (PMID 36429126, 2022). "IL-6 knockdown in BRAFi-sensitive melanoma cells resulted in significant decreases in the protein levels of both MARCKS and phospho-MARCKS (Ser-159/163)." (PMID 36551563, 2022). "Some of the cytokines produced by human melanoma cells (IL-6, IL-8, CCL5 (RANTES), CXCL1–3 (MGSA-GROa-c), and monocyte chemotactic protein-1 (MCP-1/CCL2) are associated with tumour invasiveness and aggressiveness." (PMID 35334544, 2022). "miR-128 has been found to block the p38 MAPK pathway, which inhibits the production and production of IL-6 and IL-10 while increasing the amount of IL-12 in DCs., hence boosting the anti-cancer immunity of DCs and decreasing cancer progression in melanoma." (PMID 36793341, 2022). "Fibroblasts co-cultured with invasive human melanoma cell lines showed increased expression of chemokines and cytokines such as IL-1β, IL-8, and IL-6." (PMID 36429126, 2022). "A study by Manu & Kuttan (2008), further showed that UA at a concentration of 50 μM, inhibited IL-6 production in B16F10 melanoma cells." (PMID 36558948, 2022).
melanoma (continued). "IL-6 production by moDCs also differed in the case of adenocarcinoma- and melanoma-induced regulation." (PMID 36194602, 2022). "Phosphorylation of STAT3 in melanoma activated by IL-6 can be reversed by co-treatment with apatinib and WZB117." (PMID 36188586, 2022). "Melanoma cells often express variable levels of IL-1β and IL-6, which plays an important role of cell proliferation and melanoma progression." (PMID 36132145, 2022). "Depletion of macrophages in melanoma-bearing mice reduced the levels of IL-6 during PD-1/PD-L1 blockade, suggesting that IL-6-neutralizing antibodies are potential candidates for combination with anti-PD-1 antibodies." (PMID 35663968, 2022). "Some studies have shown that high pre-treatment plasma levels of IFNγ, Interleukin 6 (IL6), and IL10 and Transforming Growth Factor β (TGF-β) are associated with response to anti-PD-1 therapy in melanoma patients." (PMID 35884403, 2022). "IL-6 secretion from BRAFi-R2 melanoma cells was significantly reduced after transfection of the IL-6-targeting siRNAs, as was the basal level of IL-6 secretion in BRAFi-sensitive melanoma cell lines." (PMID 36551563, 2022). "The most prominent components of the SASP in cytokine-treated melanoma cells were IL-1β, IL-6, and IL-8." (PMID 35563820, 2022). "HSP72 and HSP105 proteins on melanoma-derived EVs surface bind with TLR2 and TLR4 on DCs, causing the phosphorylation of ERK, JNK, p38, and NF-kB to induce expression of IL-6." (PMID 36405712, 2022). "Studies showed that the chemokines IL-6 and IL-33 induced VM in gallbladder cancer and melanoma, respectively." (PMID 35321317, 2022). "Firstly, melanoma cells were incubated with different concentrations (0, 10, 20, or 40 ng/ml) of recombinant human IL-6 for 48 h." (PMID 36188586, 2022). "Overall, these findings show that the administration of a combination of PTS and cisplatin strongly inhibited the expression of the inflammatory cytokines IL-1β, TNF-α, and IL-6 in canine melanoma." (PMID 36077992, 2022). "Monoculture CCL2 and IL-6 levels were measured to assess SK-MEL-28 vs. melanoma-conditioned macrophage protein production." (PMID 35265066, 2022). "TGFβ and IL6, representing functional cargo of EVs, were detected more abundantly in EVs than in this specific melanoma cell line lysate." (PMID 36619870, 2022). "Instead of observing a tumor-suppressive effect, accelerated tumor progression was monitored in melanoma mice treated with IL6-blocking antibodies." (PMID 36506508, 2022). "In melanoma cells, TNFα overexpression accompanied by the secretion of potent cytokine IL6 will be probably able to induce a strong inflammatory response in vivo." (PMID 33957885, 2021). "The allogeneic IL-6 transfected melanoma cells that constitute the vaccine apparently have succeeded in triggering MA-specific T cell immunity in these subjects." (PMID 33435427, 2021). "Consistent with our data in fibroblasts, knockdown of p16 in the melanoma cells also decreased IL6 and CXCL8." (PMID 33550279, 2021). "In this study, the immune-regulatory ability of melanoma CAFs was demonstrated by the ample production of several cytokines and chemokines, including IL-1α, IL-1β, IL-6, IL-8, and CXCL10." (PMID 34298873, 2021). "In this study, we observed that both recombinant and tumor-derived IL-1β specifically induce pSTAT3(Y705), creating a tumor-autoinflammatory loop, which amplifies IL-6 signaling in the human melanoma cell line 1205Lu." (PMID 34531850, 2021). "Another study showed that ILK overexpression in melanoma cells promotes angiogenesis of endothelial cells by activating the NF-κB/IL-6 signaling pathway in vitro and in vivo." (PMID 34163519, 2021). "To demonstrate that IL-6 is responsible for a metastatic switch in our experimental settings, we generated met-low melanoma overexpressing IL-6 or EV control (B16-F1-IL-6 and B16-F1-EV, respectively)." (PMID 34140316, 2021).
melanoma (continued). "In another study, crocin (250 and 500 μg/kg) attenuated VEGF, MMP-2, and MMP-9 expressions and TNF-α and IL-6 levels while it elevated IL-10 level in melanoma metastatic model in C57BL/6 mice." (PMID 34956439, 2021). "We recently reported that constitutively active NLRP3 in melanoma cells induces IL-1β and IL-6 in the host, resulting in the expansion of MDSCs." (PMID 34531850, 2021). "In engineered melanoma cells A375hTNFa, significant overexpression of inflammatory cytokine IL6 was induced (up to 17 times)." (PMID 33957885, 2021). "For example, IL6 signaling can block growth and proliferation of early stage melanoma via promoting expression of genes essential to an immune response(s), which can target early-stage cancer cells for destruction." (PMID 34411141, 2021). "As a result, it is proposed that phosphorylation of CREB in the nucleus is blocked by S100B-RSK complex, and CREB-dependent transcription of IL6 is inhibited, leading to the loss of IL6/STAT3 signaling in melanoma." (PMID 34411141, 2021). "Altogether, these findings reveal how metastatic melanoma cells amplify IL-6 signaling through an NLRP3-mediated autoinflammatory loop, which in turn, drives IL-6/STAT3 regulated immunosuppressive gene expression in PMN-MDSCs." (PMID 34531850, 2021). "In melanoma cells, inflammation/survival pathway is supported by IL6 overexpression, and activation of autophagy followed by premature senescence is initiated." (PMID 33957885, 2021). "In in vitro studies using the B16F10 melanoma cell line, high levels of corticosterone and NE induced an increased expression and secretion of IL-6." (PMID 34068618, 2021). "IL-6, highly produced also by MAFs, can promote the expression of the immunomodulatory cytokine IL-10 in melanoma cells." (PMID 34067929, 2021). "In melanoma, however, IL-6 exerts antitumor effects in the early stages of disease progression and later promotes tumor angiogenesis and the recruitment of immunosuppressive myeloid cells, such as MDSCs, to the TME." (PMID 33981768, 2021). "Under the TNFα overexpression, the mRNA of two important genes was significantly upregulated: pro-inflammatory cytokine IL6 in melanoma cells A375hTNFa, and pro-apoptotic ligand TRAIL in carcinoma cells HT29hTNFa." (PMID 33957885, 2021). "The increased amount of adipocytes in the bone marrow of obese mice was promoted through IL-6/JAK2/osteopontin axis melanoma growth in this tissue." (PMID 34068679, 2021). "It is important to define a mechanism for how elevated S100B in malignant melanoma suppresses the IL6/STAT3 pathway." (PMID 34411141, 2021). "Hyper-immunization with IL-6 transfected allogeneic melanoma cells therefore not only successfully restored T cell reactivity to MA in MP, but raised it beyond the level present in HD." (PMID 33435427, 2021). "In animal melanoma models, PD-1 inhibition using nivolumab has been shown to increase IL-6 production by macrophages in the tumor microenvironment." (PMID 33646368, 2021). "One study identified interleukin (IL)-6 as a fibroblast-derived factor involved in the growth inhibition of melanoma cells derived from RGP or early VGP primary lesions." (PMID 34067929, 2021). "This suggests the existence of the feedback loop of OPN and IL-6 in which the hormone acts both on melanoma, stimulating its proliferation, and on adipocytes, enhancing IL-6 and TNF-α synthesis." (PMID 34068679, 2021). "Further, IL6 blockade upregulated PD-L1 expression in melanoma, where the IL6-PD-L1 axis was described as a rational immunosuppressive target for anti-PD-L1 therapy." (PMID 34088360, 2021). "Compared to parental NK-92 cells, co-incubation of CD276-CAR NK-92 cells with melanoma cells significantly increased secretion of various interleukins, among others, IL-6 (98- to 317-fold) and IL-10 (6- to 15-fold)." (PMID 33925968, 2021).
melanoma (continued). "Additional studies demonstrate that the stress hormone norepinephrine stimulates the growth and metastatic capacity of melanoma cells, in part by inducing the production of IL-6, IL-8, and VEGF." (PMID 33466236, 2021). "IL-6 increases the invasiveness and motility of melanoma cells through the MAPK pathway which upregulates WNT5A, which is a major regulator of phenotype switching." (PMID 34604096, 2021). "Taken together, the data with WM115, WM793, WM1158, SK-MEL-28 melanoma cell lines support the conclusion that elevated S100B negatively regulates IL6 expression and its downstream signaling as measured via phosphorylation of STAT3." (PMID 34411141, 2021). "Dysregulation of the IL-6/gp130/STAT3 pathway is closely associated with the development of a variety of human malignancies, including melanomas." (PMID 34884773, 2021). "The noncanonical Wnt ligand Wnt5a has, for example, been shown in melanoma to induce the secretion of Exos enclosing the in this context immunomodulatory factor IL‐6 and proangiogenic VEGF and MMP2." (PMID 33207034, 2021). "Increased levels of interleukin-6 or transforming growth factor-β related to skeletal muscle atrophy contributed to poor treatment response in malignant melanoma, non-small cell lung cancer, and urothelial cancer treated with ICB." (PMID 34305941, 2021). "Overexpression of IL6 can also represent an explanation for senescence induction in melanoma because IL6 is a known initiator of senescence and an important component of SASP." (PMID 33957885, 2021). "IL-8 recruits into MME highly immunosuppressive MDSCs potentially expanded by IL-6 produced also by melanoma cells." (PMID 35011682, 2021). "In melanoma, patients with advanced stage melanoma have elevated circulating levels of the proinflammatory cytokines IL‐1β and IL‐6, which correlate with poor prognosis." (PMID 34531850, 2021). "It was reported that melanoma cells undergo TNF-α-dependent apoptosis after treatments with IL6 and the soluble form of the IL6 receptor, sIL6R." (PMID 34411141, 2021). "Recently we reported that ATF3 suppresses expression of the cytokine IL-6 in dermal fibroblasts to inhibit melanoma cell growth through paracrine pathways." (PMID 33539340, 2021). "After DHA treatment, the levels of IL-6 and IL-10 in serum and melanoma of melanoma bearing mice are significantly decreased, while IFN-γ is significantly increased." (PMID 34692496, 2021). "XBP1s binds to putative UPR elements containing the ACGT core sequence of the Il6 promoter, thereby activating the transcription of Il6 in melanoma cells." (PMID 34356855, 2021). "Treatment with blocking antibodies targeting CXCR4, the receptor for SDF-1, VEGF-A or IL-6, has been shown to reduce melanoma cell invasiveness induced by the conditioned media from hypoxic activated fibroblasts." (PMID 34067929, 2021). "A relatively long time ago, an increased level of IL-6 in serum was observed in patients with melanoma." (PMID 34068679, 2021). "Melanocytes stimulated by adipocyte-derived IL-6 reduce melanogenesis, which supports the thesis concerning the paracrine differentiation of melanoma cells under the influence of adipocytes." (PMID 33430277, 2021). "IRE1α-induced IL-6 has been implicated in promoting carcinogenesis of HCC and proliferation of melanoma." (PMID 34295814, 2021). "IL-6 sends signals directly to melanoma cells through the JAK/STAT3 pathway, which leads to increased tumor production (immunosuppressive cytokines)." (PMID 33540700, 2021). "In parental melanoma cells A375, zafirlukast itself, surprisingly, dramatically increased expression of TNFα mRNA (up to 100 times) and also increased IL6 expression." (PMID 33957885, 2021). "Overall, these data confirm the in vitro observation and suggest the induction of IL‐6/STAT3 following NLRP3 inflammasome activation as an integral driver of melanoma progression." (PMID 34531850, 2021).
melanoma (continued). "The upregulation of IL-1β, IL-2, IL-6, and IL-12 mRNA expression was significant in PBMCs co-cultured with melanoma cells depigmented by both tyrosinase inhibitors, compared to pigmented cells." (PMID 34072104, 2021). "Collectively, these data continue to support a mechanism in which elevated S100B found in malignant melanoma negatively regulates the IL6/STAT3 pathway and that functional IL6 can be restored when S100B expression is inhibited." (PMID 34411141, 2021). "A similar effect in melanoma has interleukin-6 (IL-6), vascular endothelial factor (VEGF), and matrix metalloproteinases (MMP) transported by exosomes." (PMID 32537468, 2020). "Logistic regression revealed that the key genes responsible for these results were CXCL9 and SPP1 for melanoma and IL6 and CXCL13 for LSCC." (PMID 32383556, 2020). "Our data also revealed the importance of IL‐10 and IL‐6 in predicting metastatic progression, albeit they provide a subleading and fluctuating contribution to melanoma outcome prediction compared to Breslow thickness and serum levels of IL‐4, GM‐CSF, and DCD." (PMID 32485045, 2020). "Statistically significant differential plasma expression in melanoma patients vs. controls has been reported for IL-2, IL-6, and IL-10." (PMID 33302400, 2020). "Of note, physical activity suppresses subcutaneous B16 melanoma tumor growth through epinephrine- and IL-6-dependent NK cell mobilization and redistribution in mice, suggesting a rather activating effect of IL-6 on NK cells." (PMID 32231659, 2020). "OSM reduces the growth of human melanoma xenograft tumors in a mouse model in an IL-6-dependent manner." (PMID 33216732, 2020). "Preisner and colleagues used qRT-PCR to analyze the expression of 229 tumor-promoting genes in melanoma cells cocultured with ADSCs and found similar cytokines and growth factors, such as IL6, CXCL12, VEGF, and HGF69." (PMID 32848147, 2020). "IL-6 has been shown to play a promoting role in the pathogenesis and development of malignancies in many kinds of tumors, including melanoma, and was also shown to be highly expressed by CAFs contacting different tumor types." (PMID 32373541, 2020). "CRP is synthetized in response to cytokines such as interleukin-6 (IL-6), which is produced by melanoma cells." (PMID 32631431, 2020). "Functionally, the melanoma-induced CD14+ DCs described here, express genes (such as SSP1, PTGS2, IL-6) previously associated with immunosuppressive myeloid cells and, like monocytes and macrophages, have poor T-cell stimulatory ability." (PMID 32488012, 2020). "Particularly interesting is the strong correlation of IL-6 to TNF-α in the melanoma samples; these two molecules are known to control the ability to evade the immune system control in a PDL-1-dependent manner." (PMID 33302400, 2020). "IL-6, a pro-inflammatory cytokine, has been well-documented to play important roles in development and progression of melanoma, and its expression was markedly reduced in ATF3-overexpressing HDFs." (PMID 32373541, 2020). "We have confirmed that pro-inflammatory cytokine IL-6 significantly enhances melanoma invasion to the extracellular matrix in our model." (PMID 33182777, 2020). "To date, previous studies have shown that EDPs and/or VGVAPG peptide increase the production and/or secretion inflammatory markers such as IL-1α, IL-1β, and IL-6 in ligamentum flavum cells, synovial cells, and melanoma cell lines." (PMID 32463311, 2020). "For more insight please see Transcripts 202 and 205 of IL-6 confer resistance to Vemurafenib by reactivating the MAPK pathway in BRAF(V600E) mutant melanoma cells." (PMID 32382617, 2020). "IL-6 plays a central role in melanoma development and enhances the IL-10 production via STAT3-dependent signaling." (PMID 32508531, 2020). "We observed that CXCL1 was predominantly produced by the melanoma cells, while IL6 and LIF were expressed mainly by the fibroblasts and CXCL8 by both cell types." (PMID 33182777, 2020).